KCNQ2 (potassium voltage-gated channel subfamily Q member 2)
Description:
Pore-forming subunit of the voltage-gated potassium (Kv) M-channel which is responsible for the M-current, a key controller of neuronal excitability. M-channel is composed of pore-forming subunits KCNQ2 and KCNQ3 assembled as heterotetramers. The native M-current has a slowly activating and deactivating potassium conductance which plays a critical role in determining the subthreshold electrical excitability of neurons as well as the responsiveness to synaptic inputs. KCNQ2-KCNQ3 M-channel is selectively permeable in vitro to other cations besides potassium, in decreasing order of affinity K(+) > Rb(+) > Cs(+) > Na(+). M-channel association with SLC5A3/SMIT1 alters channel ion selectivity, increasing Na(+) and Cs(+) permeation relative to K(+). Suppressed by activation of the muscarinic acetylcholine receptor CHRM1.
Synonyms: Kv7.2; ENB1; BFNC; KCNA11; HNSPC; DEE7; EBN; EBN1
Tractability: Small molecule: an approved drug acts on it; a structure with a bound ligand is known; a high-quality ligand is known; it belongs to a druggable protein family. Antibody: UniProt places it where antibodies can reach, with high confidence; its Gene Ontology location is reachable by antibodies, with high confidence; UniProt predicts a signal peptide or a membrane-spanning region. PROTAC: UniProt records ubiquitination sites on it; ubiquitination databases record sites on it; its protein half-life has been measured; a small molecule that binds it is known.
Target class: Potassium channels; Ion channel; Voltage-gated ion channel; Voltage-gated potassium channel
Chemical probes: ML213, ML252 (high quality)
Gene: Protein-coding gene on chromosome 20 (63,400,208 to 63,472,677, reverse strand). Ensembl gene ENSG00000075043.
Subcellular location: Cell membrane
Subcellular location (Human Protein Atlas): Endoplasmic reticulum
Pathways (Reactome):
Developmental Biology: Interaction between L1 and Ankyrins
Neuronal System: Voltage gated Potassium channels
Gene Ontology:
Molecular function: ankyrin binding; calmodulin binding; protein binding; voltage-gated monoatomic cation channel activity; voltage-gated potassium channel activity; monoatomic ion channel activity; potassium channel activity
Biological process: potassium ion transmembrane transport; action potential; chemical synaptic transmission; nervous system development; monoatomic ion transport; potassium ion transport; transmembrane transport
Cellular component: plasma membrane; voltage-gated potassium channel complex; axon initial segment; membrane; node of Ranvier; synapse
Genetic constraint (gnomAD): Loss-of-function variants: 15 observed, 78.32 expected, observed/expected ratio (o/e) 0.19, 90% interval 0.13 to 0.29. The synonymous counts are far from expectation, so gnomAD's model fits this gene poorly and the ratio says little. Missense variants: 788 observed, 1,129.2 expected, observed/expected ratio (o/e) 0.7, 90% interval 0.66 to 0.74. Synonymous variants: 599 observed, 508.24 expected, observed/expected ratio (o/e) 1.18, 90% interval 1.1 to 1.26.
Gene-disease validity (ClinGen):
ClinGen rates the evidence that KCNQ2 causes each of these diseases.
complex neurodevelopmental disorder (autosomal dominant): Definitive. A disorder that involves more than one phenotype associated with the central nervous system, including but not limited to intellectual disability, autism, and seizures (epilepsy).
neonatal-onset developmental and epileptic encephalopathy (autosomal dominant): Definitive. A complex neurodevelopmental disorder characterized by a neonatal onset of recurrent seizures, an abnormal neonatal electroencephalographic background with multifocal epileptiform discharges, excessive discontinuity, and/or burst-suppression patterns, and encephalopathy.
Homologues: Orthologues: chimpanzee KCNQ2 (99% identical), guinea pig KCNQ2 (96% identical), dog KCNQ2 (96% identical), mouse Kcnq2 (95% identical), rat Kcnq2 (95% identical), pig KCNQ2 (94% identical), tropical clawed frog kcnq2 (83% identical), zebrafish kcnq2b (78% identical), zebrafish kcnq2a (64% identical). Paralogues in human: KCNQ3 (47% identical), KCNQ5 (46% identical), KCNQ4 (41% identical), KCNQ1 (28% identical), KCNB2 (15% identical), KCND1 (12% identical), KCND2 (12% identical), KCND3 (12% identical), KCNC3 (12% identical), KCNC2 (11% identical), KCNA4 (11% identical), and 19 more.
Diseases named in the same sentence as KCNQ2 in open-access papers:
KCNQ2 is named in the same sentence as 146 diseases in open-access papers, as found by Europe PMC text mining. Sharing a sentence is not in itself a finding about the gene and the disease. The quoted sentences say what the papers report.
epilepsy (178 papers, 2009 to 2026). A brain disorder characterized by episodes of abnormally increased neuronal discharge resulting in transient episodes of sensory or motor neurological dysfunction, or psychic dysfunction. "KCNQ2 variants cause a spectrum of neonatal epilepsies, ranging from self-limited familial neonatal-infantile epilepsy (SeLFNIE) to early infantile developmental and epileptic encephalopathy (EIDEE)." (PMID 41742307, 2026). "We also found that most KCNQ2-associated epilepsies responded well to sodium channel blockers, especially OXC." (PMID 40236662, 2025). "KCNQ2 loss-of-function (LoF) variants are associated with self-limiting neonatal epilepsy, while variants resulting in dominant-negative effects cause severe neonatal-onset developmental and epileptic encephalopathy." (PMID 40399560, 2025). "With the development of genetic technology, KCNQ2 mutations leading to different severity of epilepsy phenotypes are being reported more frequently." (PMID 40342533, 2025). "Mutations in the SCN1A gene are a major cause of severe epilepsy in infants, while mutations in KCNQ2 and KCNQ3 genes increase neuronal excitability, affecting seizure frequency and type." (PMID 40520613, 2025). "KCNQ2 is deeply involved in brain development of newborns and responsible for most cases of youth epilepsy events either when its function is inhibited (loss of function) or activated (gain of function)." (PMID 41364066, 2025). "Pathogenic KCNQ2 variants are associated with neonatal epilepsies, ranging from self-limited neonatal epilepsy to KCNQ2–developmental and epileptic encephalopathy (DEE)." (PMID 39796146, 2024). "The mechanism of epilepsy in the KCNQ2 GoF phenotype is unclear, since these variants should lead to excessive inhibition of neuronal firing and hence a lesser tendency to seizures." (PMID 39175503, 2024). "The patient bearing the p.Arg144Gln KCNQ2 variant had epilepsy, which deteriorated when treated with the sodium channel blocker carbamazepine, suited for LoF variants." (PMID 39175503, 2024). "In the present study, we reported the clinical–genetic features of three unrelated probands, with two novel variants and one already reported KCNQ2 variant, and a highly variable phenotypic spectrum of epilepsy." (PMID 39796146, 2024). "The KCNQ2 protein regulates action potential firing, and mutations in its gene are associated with epilepsy and neuropathic pain." (PMID 38737299, 2024). "We previously demonstrated that reducing Scn8a expression is therapeutic in Scn1a+/− mice and in mice with epilepsy caused by loss of the potassium channel genes Kcna1 and Kcnq2." (PMID 37901435, 2023). "To date, at least one hundred ninety-four cases of KCNQ2-related epilepsy have been reported with mutations distributed all over the gene leading to varying severity." (PMID 36849527, 2023). "KCNQ2 epilepsy-causing variants can be classified according to diverse parameters, including location, function, and related clinical phenotypes." (PMID 36932231, 2023). "Generally, it is considered that missense mutations found in KCNQ2-related epilepsy cases were mainly located in several hotspots, including the S4 voltage sensor, the pore, and the calmodulin-binding helix." (PMID 36932231, 2023). "Variants in genes encoding potassium channels induce different forms of epilepsy, ranging from benign familial neonatal seizures (KCNQ2/3, encoding KV7.2/3) to severe developmental and epileptic encephalopathies (KCNA2, encoding KV1.2)." (PMID 37360341, 2023). "Mutations in the KCNQ2 gene, which encodes a potassium channel crucial for neuronal excitability, have been linked to a specific type of epilepsy called Benign Familial Neonatal Epilepsy (BFNE)." (PMID 38069426, 2023). "This study expands the mutational spectrum of KCNQ2- related epilepsy and their functional consequences provide insights into their pathomechanism." (PMID 36849527, 2023).
epilepsy (continued). "Whereas, trios NGS (epilepsy panel) revealed a de novo heterozygous mutation in Exon 5 of the KCNQ2 gene (NM_172107.4; NP_742105.1): c.740C>T/(p.Ser247Leu), affecting a highly conserved aminoacidic region and predicted to be deleterious in silico programs." (PMID 35401395, 2022). "We validated use of automated patch clamp for KCNQ2 by performing initial experiments on 18 epilepsy-associated variants previously shown to have deleterious functional consequences, and our results were largely concordant with the prior work." (PMID 35104249, 2022). "Pathogenic variants in KCNQ2 are a frequent cause of early-onset monogenic epilepsy and neurodevelopmental disorders." (PMID 35104249, 2022). "Epilepsy caused by the KCNQ2, KCNQ3, PRRT2, SCN2A and SCN8A gene are relatively benign with mild symptoms and consequences." (PMID 35571021, 2022). "KCNQ2 gene-associated epilepsies are very rare and more common presentations are self-limited familial neonatal epilepsy (SLFNE) and early infantile epileptic encephalopathies (EIEE)." (PMID 36726904, 2022). "VCF reveals different mechanisms by which different epilepsy-associated mutations affect KCNQ2 channel voltage-dependent gating." (PMID 35642783, 2022). "Here, we define the parameters of voltage sensor movements in wt-KCNQ2 and channels bearing epilepsy-associated mutations using cysteine accessibility and voltage clamp fluorometry (VCF)." (PMID 35642783, 2022). "The KCNQ2/3 heteromeric channel has unique kinetic properties associated with the native M-current, which is strongly associated with epilepsy and ASD comorbidities, as well as a spectrum of developmentally regulated diseases in the brain." (PMID 36499620, 2022). "We observed that the majority of these KCNQ2 epilepsy-associated variants exhibit properties consistent with loss-of-function that can be predicted to cause impaired neuronal M-current." (PMID 35104249, 2022). "The first patient presented with neonatal epilepsy with an onset during the first week of life, which was later ascribed to a KCNQ2 pathogenic variant paternally inherited." (PMID 35401395, 2022). "Patients with mutations in KCNQ2 appear to have a slightly more favorable prognosis with respect to epilepsy and, in some cases, better development with achievement of motor skills and simple communication." (PMID 38835873, 2022). "Next, we investigate the mechanism(s) by which the epilepsy-associated mutations R198Q and R214W alter KCNQ2 channel voltage-dependent activation." (PMID 35642783, 2022). "We here describe the mechanisms underlying voltage sensor movement in KCNQ2 channels relevant to understand epilepsy-associated KCNQ2 mutations." (PMID 35642783, 2022). "In this study, we undertook the largest single effort to determine the functional and pharmacological properties of epilepsy-associated KCNQ2 variants in both the homozygous and heterozygous states." (PMID 35104249, 2022). "Because retigabine is a potential therapeutic agent for KCNQ2-associated epilepsy, we investigated its effect on epilepsy-associated variants expressed in the heterozygous state." (PMID 35104249, 2022). "Previous studies indicated that KCNQ2 missense variants were associated with severe epilepsy phenotype and poor neurological outcomes because of dominant-negative effects, whereas truncating variants were likely to be KCNQ2-BFNE." (PMID 35557555, 2022). "Studies suggested that drugs acting on sodium channels should be considered as first-line treatment in patients with KCNQ2-associated epilepsy." (PMID 34107977, 2021). "Mutations in the KCNQ2 gene associated with human epilepsy have been suggested to cause misfolding of the encoded Kv7.2 channel." (PMID 34020651, 2021).
epilepsy (continued). "The overlap between epilepsy mutation hotspots and the PIP2 binding domains identified in our study underscores the critical role of PIP2 in the pathophysiological mechanism underlying KCNQ2-related epilepsy." (PMID 34650221, 2021). "Recent work has shown that KCNQ3 dysfunction leads to pharmaco-dependent epilepsy in patients lacking both functional Kcnq3 copies, which is distinct from the pharmaco-resistant epilepsy caused by KCNQ2 dominant-negative variants." (PMID 33863780, 2021). "For genes associated with neonatal and infantile epilepsies, including KCNQ2, KCNT1, PRRT2, and SCN8A, we found that EMR usage was concentrated in the first year of life." (PMID 34031551, 2021). "KCNQ2 variants are associated with a wide phenotypic spectrum ranging from an age-dependent, self-limiting epilepsy, to a severe DEE but also an intermediate phenotype in terms of intellectual outcomes and time to reach seizure freedom." (PMID 34163418, 2021). "Current anti-epileptic drugs are ineffective in treating many patients with KCNQ2 EE variants, posing a critical need to understand how EE mutations disrupt Kv7 channels and lead to severe symptomatic epilepsy." (PMID 32179837, 2020). "The phenotypes and genotypes of KCNQ2-associated epilepsy continue to be investigated, and some case series and functional studies have been conducted." (PMID 32770121, 2020). "Pathogenic loss-of-function variants in KCNQ2 have been linked to epilepsy since 1998, and there is ample functional evidence showing that dysfunction of the channel indeed results in neuronal hyperexcitability." (PMID 33192566, 2020). "A prominent epilepsy-associated protein appeared in this analysis, potassium ion-channel protein KCNQ2, whose gene plays important roles, when mutated, in the development of infancy epilepsies like benign familial neonatal convulsions (BFNC,)." (PMID 32751954, 2020). "About 163 (1.9%) of the 8,565 patients in one study with epilepsy and neurodevelopmental disorders had detectable KCNQ2 mutations." (PMID 31199083, 2019). "Our most important finding is that KCNQ2 mutations led to a variety of phenotypes in childhood epilepsy, for example, neonatal‐onset EE, BFNC, and CSWS." (PMID 31199083, 2019). "Epilepsy caused by a KCNQ2 gene mutation usually manifests as neonatal seizures during the first week of life." (PMID 31199083, 2019). "Further, hypomorphic mutations in either KCNQ2, an established epilepsy-associated gene, or KCNQ3 are reported to be highly penetrant." (PMID 30148849, 2018). "We identified only two reported cases with ESESS/CSWSS/epilepsy-aphasia spectrum who had KCNQ2 mutations." (PMID 29976148, 2018). "Retigabine (RTG), a Kv7.2/ Kv7.3-channel opener, seems to be a rational antiepileptic drug for epilepsies caused by KCNQ2 mutations." (PMID 26910900, 2016). "Given the efficacy of RTG in animal models of neonatal epilepsy caused by KCNQ2 mutations, potassium channel openers should be considered as a therapeutic option for BFNE/BNE and perhaps even for EOEE." (PMID 26910900, 2016). "Taken together, these previous findings and our present study suggest high potential of RTG in treating epilepsy resulting from KCNQ2 mutations." (PMID 26910900, 2016). "Missense mutations in KCNQ2, the human ortholog of Kcnq2, have been linked to seizure disorders including benign familial neonatal epilepsy (BFNE, OMIM #269720)." (PMID 24586341, 2014). "Mutations in both helices A and B have been linked to KCNQ2-related epilepsies, with a wide range of phenotypic manifestations." (PMID 24489773, 2014). "KCNQ2 is frequently found mutated de novo in early onset epileptic encephalopathies, especially if the epilepsy begins within the first week of life." (PMID 23692823, 2013). "KCNQ2 or KCNQ3 loss-of-function mutations result in a developmental form of epilepsy called Benign familial neonatal convulsions." (PMID 23638087, 2013).